S100A8 (S100 calcium binding protein A8)
Diseases named in the same sentence as S100A8 in open-access papers (continued):
Sharing a sentence is not in itself a finding about the gene and the disease.
tendinopathy (6 papers, 2019 to 2024). "This chemotaxis and cytokine modulation are particularly prominent in the early stages of tendinopathy, establishing a mechanistic link between S100A8 and S100A9 proteins and RC tendinopathy development." (PMID 38248784, 2024). "We identified S100A8 immunopositive staining which colocalized with the macrophage marker CD163 in early-stage tendinopathy." (PMID 38655164, 2022). "During tendinopathy conditions, the inductive expression and secretion of S100A8 and S100A9 affect the activation of local tenocytes, boosting immune cell recruitment to the injured site and altering the stromal microenvironmental cue." (PMID 35892571, 2022). "During tendinopathy, the S100A8/A9 heterodimer (calprotectin) has an immunomodulatory effect that stimulates the innate immune response and controls the stromal microenvironment." (PMID 35892571, 2022). "S100A8 mRNA expression is significantly upregulated in early tendinopathy compared with control (p < 0.05)." (PMID 30728384, 2019). "We propose S100A8 & A9 participate in early pathology by modulating the stromal microenvironment and influencing the inflammatory profile observed in tendinopathy." (PMID 30728384, 2019). "We have identified that S100A8 & A9 play an important immunomodulatory role in tendinopathy through activation of the innate immune system and manipulation of the stromal microenvironment." (PMID 30728384, 2019). "Coupled with confirmation of passive release of CCL2 in response to acute injury our data supports the concept of S100A8 & A9 acting as functional tissue alarmins in tendinopathy by promoting immune cell recruitment." (PMID 30728384, 2019). "Semi quantitative analysis again suggested that S100A9 (9% early tendinopathy, 5% late tendinopathy, % of cells stained positive) was more frequently expressed that S100A8 (4% early tendinopathy, 1% late tendinopathy, % of cells stained positive) in tissue biospies." (PMID 30728384, 2019). "Our data confirms the presence of S100A8 and S100A9 in tendinopathy and suggests they actively contribute to pathological proceedings in the early stages of disease." (PMID 30728384, 2019). "Our study has established the presence of S100A8 and S100A9 in a human model of tendinopathy, most notably in the early stages of disease." (PMID 30728384, 2019). "We next noted significantly greater protein expression of the alarmin molecules S100A8 and S100A9 in the early tendinopathy group compared with the control group (p < 0.05)." (PMID 30728384, 2019). "Since S100A8/A9 is involved in inflammatory processes induced either by pathogens or in chronic inflammation such as tendinopathy, it is an indicator of inflammation rather than one diagnostic for a specific pathogen." (PMID 37831367, 2024). "Furthermore, S100A8 and S100A9 are products of neutrophils and monocytes and are known to modulate the early stromal microenvironment during the development of tendinopathy and to influence the composition of the inflammatory cell infiltrate." (PMID 35039073, 2022). "We observed greatest significant upregulation of S100A8 and S100A9 in early tendinopathy and a relative absence of S100A8 mRNA expression in late tendinopathy suggesting these alarmins are key regulators in the early stage of disease." (PMID 30728384, 2019). "Recent investigations have established tendinopathy as an alarmin-mediated pathology thus we sought to characterize the expression of S100A8 and S100A9 in human tendinopathy and explore their biological significance in the context of inflammation and matrix regulation." (PMID 30728384, 2019). "This implies that S100A8/S100A9 modulates the inflammatory profile through a positive feedback mechanism, involving increased recruitment of leukocytes and the release of pro-inflammatory cytokines from tenocytes, sustaining the inflammatory response in the early stages of tendinopathy." (PMID 38248784, 2024).
triple-negative breast carcinoma (6 papers, 2018 to 2024). An invasive breast carcinoma which is negative for expression of estrogen receptor (ER), progesterone receptor (PR), and human epidermal growth factor receptor 2 (HER2). "The results showed that ER-negative and triple-negative breast cancer (TNBC) patients had significantly higher expression of S100A8 than patients with other subtypes." (PMID 30456203, 2018). "The study further reported S100A8’s elevated levels in correlation with estrogen receptor-negative and triple-negative breast cancer clinical subtypes." (PMID 35471994, 2022).
type 1 diabetes (6 papers, 2016 to 2026). "Studies of type 1 diabetic (T1D) mice uncovered that hyperglycemia stimulates neutrophils to produce S100A8/A9." (PMID 27447612, 2016). "(2013) reported that S100A8/S100A9 acted through the receptor for advanced glycation end-products (RAGE) on CMPs to promotegranulocyte–macrophage colony-stimulating factor (GM-CSF) production that in turn stimulated GMP proliferation and myelopoiesis in type 1 diabetic mice and apoE−/− mice." (PMID 36866528, 2023).
acute pancreatitis (5 papers, 2018 to 2026). An acute inflammatory process that leads to necrosis of the pancreatic parenchyma. "Rapidly internalized by alveolar macrophages, acute pancreatitis-derived exosomes delivered S100A8/A9 to induce pyroptosis." (PMID 42128052, 2026). "However, several pieces of research have also illustrated that S100a8/a9 is upstream of the IL-17 signaling pathway, such as in acute pancreatitis." (PMID 35741040, 2022). "S100A8 and S100A9 are overexpressed in acute pancreatitis (AP), CP, and PC tissues, but they are rarely expressed in CP tissues with severe fibrosis, normal pancreatic tissues, and ductal cells." (PMID 34527585, 2021).
bacteremia (5 papers, 2021 to 2025). "The eight differentially expressed genes (DEGs) as key diagnostic markers for bacterial sepsis: FTH1, B2M, NAMPT, KLF6, SRGN, S100A6, S100A9, and S100A8." (PMID 41303672, 2025). "We have recently shown that gene expression levels of S100A8/A9 in the early stages of S. aureus bacteremia predict the later development of septic arthritis in a mouse model." (PMID 39204252, 2024). "To further study whether S100a8 and a9 gene expression at the early stage of bacteremia can predict the later development of septic arthritis, we compared mRNA levels of S100a8 and a9 on day 2 after infection between mice infected with Newman WT strain and mice infected with ΔsrtA/B strain." (PMID 37396347, 2023). "However, it is still unknown whether S100A8/9 can be used as a predictor for septic arthritis in bacteremia patients." (PMID 37396347, 2023).
bacterial pneumonia (5 papers, 2013 to 2025). Acute infection of the lung parenchyma caused by bacteria (e.g., Streptococcus pneumoniae, Haemophilus influenzae, Chlamydia pneumoniae, Mycoplasma pneumoniae, and Legionella pneumophila). "Therefore, since PCT cannot identify mild cases, combining with S100A8/A9 during the disease course could improve the diagnostic efficiency of bacterial pneumonia and predict the disease in time to guide appropriate treatment." (PMID 37180431, 2023). "Severe bacterial pneumonia was marked by an inflammatory cytokine storm resulting from systemic upregulation of S100A8/A9 and CXCL8, primarily due to specific macrophage and neutrophil subsets." (PMID 39757231, 2025). "Deletion of S100A8/A9 promotes progression of bacterial pneumonia and septic patients showed continuous increase of S100A8/A9." (PMID 37624851, 2023). "Animal studies have demonstrated that S100A8 plays a critical role in promoting the transepithelial migration of leukocytes into the airspaces during bacterial pneumonia, whereas its blockade dramatically diminishes this inflammatory process." (PMID 23505561, 2013).
cardiac hypertrophy (5 papers, 2021 to 2025). "The present findings expand the knowledge of how S100A8/A9 in myeloid cells contributes to the TAC-induced transition from cardiac hypertrophy to HF and reveal that S100A8/A9 plays a critical role in the pathogenesis of HF." (PMID 40860162, 2025). "In conclusion, the present study revealed a novel function of S100A8/A9 in myeloid cells in the transition from pressure overload-induced cardiac hypertrophy to HF." (PMID 40860162, 2025). "TAC-induced early cardiac infiltration of neutrophils highly expressing S100A8/A9 contributes acute inflammation and adaptive cardiac hypertrophy." (PMID 40860162, 2025). "First, the exploration of the role of S100A8/A9 in cardiac hypertrophy and dysfunction was limited to a mouse model induced by TAC." (PMID 40860162, 2025). "While typically low in cardiomyocytes, S100A8 expression increases in response to thyroid hormone treatment in neonatal rat cardiomyocytes, contributing to cardiac hypertrophy via the MyD88/NF-κB pathway." (PMID 39175627, 2024). "Recently, S100a8 was reported to be one of the genes that was specifically induced during the regression of cardiac hypertrophy in a myocardial hypertrophic preconditioning model." (PMID 35907209, 2022). "Previous studies have indicated that pretreatment with S100a8 recombinant protein attenuated norepinephrine-induced cardiac hypertrophy and subsequently reduced the expression of calcineurin and NFAT." (PMID 35907209, 2022). "Collectively, our findings showed that, through inhibiting S100a8, miR-21 triggers cardiac hypertrophy and fibrosis under pressure overload pathophysiology." (PMID 35907209, 2022). "However, the potential role of S100A8/A9 in models of pressure overload-induced cardiac hypertrophy has received little attention." (PMID 40860162, 2025). "To explore whether S100A8 or S100A9-mediated inflammation induces cardiac hypertrophy in the early phase of HF, we applied WT and S100A9-KO mice and subjected them to sham or TAC surgery for 1 week." (PMID 40860162, 2025). "Therefore, they exhibited upregulation of S100A8/A9, which led to exacerbation of inflammation, cardiac hypertrophy and fibrosis via activation of the NF-κB/NLRP3, AKT/Calcineurin A and TGF-β/Smad2 signaling pathways." (PMID 40860162, 2025). "Myocardial hypertrophy is a pivotal aspect of HF, and S100A8/A9 may be influenced by diverse physiological conditions, leading to varied responses in the pathogenesis of myocardial hypertrophy." (PMID 39175627, 2024). "However, the significance of S100A8/A9 in the transition from adaptive to maladaptive cardiac hypertrophy caused by pressure overload has not been completely elucidated." (PMID 40860162, 2025). "As miR-21 mediates cardiac hypertrophy involving S100a8, which participates in modulating the NF-κB/NFAT pathway, we found that, by suppressing S100a8, miR-21 triggers cardiac hypertrophy under pressure overload." (PMID 35907209, 2022). "Collectively, these data indicated that increased expression of S100A8 and S100A9 in neutrophils may play a major role in the early stage of adaptive cardiac hypertrophy, whereas S100A8 and S100A9 upregulation in macrophages may facilitate cardiac hypertrophy in the late stage of TAC-induced HF." (PMID 40860162, 2025).
cardiomyopathy (5 papers, 2016 to 2025). A disease of the heart muscle or myocardium proper. "S100a8/a9 inhibition by ABR‐238901 showed a similar heart protective effect against DOX‐induced cardiomyopathy to LIPUS treatment." (PMID 38023700, 2023). "Notably, S100A8 and S100A9 were found to have a unique specific expression pattern that was coincident with the DOX-induced cardiomyopathy in diabetic hearts." (PMID 27547188, 2016).
carotid atherosclerosis (5 papers, 2013 to 2021). A thickening and loss of elasticity of the walls of carotid arteries that occur with formation of atherosclerotic plaques. "In human, several S100 proteins, including S100A7, S100A8, S100A9, and S100A12, are linked with the severity of coronary and carotid atherosclerosis." (PMID 30886860, 2019). "In humans, S100A8/A9 correlates with the extent of coronary and carotid atherosclerosis and with a vulnerable plaque phenotype." (PMID 24453429, 2013).
emphysema (5 papers, 2018 to 2024). "While thymic tissue mass was later restored, the lungs of IAV-infected S100a8-Cre/Inhbafl/fl animals were characterized by persistent tissue remodeling with focal regions of emphysema-bullae, at 35 days p.i.." (PMID 38476229, 2024). "On the one hand, S100A8 protects alveolar epithelial type II cells against cigarette smoke-induced injury and emphysema." (PMID 33567747, 2021). "Considering all of this evidence, smoking leads to a higher S100A8 expression as a defense mechanism for protecting from smoke-induced alveolar type II cell injury and emphysema pathogenesis, according to in vitro studies and in vivo animal models." (PMID 33567747, 2021). "Based on our findings on DAMPs markers, aging alone influenced the release of S100A8 in chronic CS-induced COPD/emphysema." (PMID 29899396, 2018).
end-stage renal disease (5 papers, 2006 to 2025). "The plasma S100A8/A9 level had been proven to be a useful marker for inflammation in patients with end-stage renal disease and on chronical diagnosis." (PMID 38110934, 2023).
food allergy (5 papers, 2016 to 2021). Gastrointestinal disturbances, skin eruptions, or shock due to allergic reactions to allergens in food. "Besides, the roles of serum S100A8/A9 and inflammatory-related factors in food allergies and possible underlying mechanisms were preliminary explored, which provided more basic data and laboratory evidence regarding food allergies." (PMID 33499808, 2021). "The role of serum S100A8/A9 in intestinal inflammation has been confirmed, and its role in food allergy is currently being investigated." (PMID 33499808, 2021). "The role of S100A8/A9 in the development of human food allergies remains to be investigated in further research." (PMID 33499808, 2021). "The increase in S100A8/A9 amplifies the cascade of allergic and inflammatory factors in food allergies." (PMID 34903286, 2021). "In food allergies, S100A8/A9 in the feces and TLR4, NF-κB, IL-1β, and IL-6 in the liver and jejunum are elevated, which indicates that S100A8/A9 regulates the balance of Th1/Th2 and amplifies the allergic cascade." (PMID 29942307, 2018). "Further research is needed to understand the role of S100A8/A9 in food allergies." (PMID 33499808, 2021). "This study found that S100A8/A9 is a key contributor in promoting food allergy development." (PMID 28454097, 2017). "It is not difficult to speculate that besides being an inflammatory factor, S100A8/A9 has some role in the process of a food allergy, possibly as a trigger that amplifies cascade reaction of allergic-related and inflammatory factors in allergic processing." (PMID 28454097, 2017). "S100A8/A9 and inflammatory-related factors, including TLR4, NF-κB, TNF-α, IL-6 and IL-1β, is closely related to food allergies." (PMID 33499808, 2021). "The level of fecal S100A8/9 in infants with food allergy is twice as high as that of infants without food allergy, and S100A8/A9 may be a key contributor in promoting food allergy development in children." (PMID 29942307, 2018).
glomerulonephritis (5 papers, 2017 to 2023). A renal disorder characterized by damage in the glomeruli. "Serum S100A8 and S100A9 levels reflect disease activity in ANCA-associated vasculitis, glomerulonephritis and systemic lupus erythematosus." (PMID 29795379, 2018). "In fact, studies on S100A8/9 in glomerulonephritis suggest that increased S100A8/9 expression actually reflects a change in the immune cell phenotype versus a simple increase in the number of infiltrating immune cells within the kidney." (PMID 29065913, 2017). "Another study proved that conditional ablation of the S100A8 gene in myeloid cells or general knockout of the S100A9 gene in mice could ameliorate glomerulonephritis and obstructive nephropathy phenotypes due to inflammatory response inhibition." (PMID 38110934, 2023). "Whereas S100A8/9 and S100A12 are predominantly phagocyte-specific proteins, S100A4 (also known as fibroblast-specific protein 1 or metastasin) is more widely expressed and has demonstrated correlation with disease activity in various forms of glomerulonephritis." (PMID 29065913, 2017).
irritable bowel syndrome (5 papers, 2014 to 2022). Irritable bowel syndrome (IBS) is a chronic functional condition of the lower gastrointestinal (GI) tract characterized by abdominal pain or discomfort and disordered bowel habit (diarrhea, constipation, or fluctuation between the two). "Importantly, the detection of S100A8/A9 in feces can be used to differentiate IBD from irritable bowel syndrome." (PMID 36235175, 2022). "In addition, fecal S100A8/A9 can be used to differentiate IBD from irritable bowel syndrome with a high level of accuracy." (PMID 25860480, 2015). "Because there is no epithelial inflammation in irritable bowel syndrome, fecal S100A8/A9 concentrations are low." (PMID 26799323, 2016).
kidney stones (5 papers, 2013 to 2023). "Our previous study demonstrated that urinary exosomes from kidney stone patients were rich in S100A8 and S100A9." (PMID 34395096, 2021). "In addition to analyses of human fluids and kidney stones, cell culture studies have revealed various PTMs on S100A8 and S100A9." (PMID 36826733, 2023). "With the development of mass spectrometry, proteomic studies have frequently identified calgranulins S100A8 and S100A9 in the kidney stone matrix." (PMID 37051106, 2023). "Renal sources and important regulators for S100A8 and S100A9 in nephrolithiasis were explored in this study." (PMID 37051106, 2023). "M1-polarized macrophages were the predominant cell type expressing S100A8 and S100A9 in the kidneys of nephrolithiasis patients." (PMID 37051106, 2023). "To further study the role of S100A8 and S100A9 in nephrolithiasis, we think two important questions should be addressed first." (PMID 37051106, 2023). "In this study, the expression of S100A8 and S100A9 in renal tissue was also found to be elevated in kidney stone patients." (PMID 34395096, 2021). "Immunohistochemistry results showed that the expression of S100A8, S100A9 and OPN was significantly increased in renal tissue from kidney stone patients." (PMID 34395096, 2021). "It is unclear whether S100A8 and S100A9 from M1-polarized macrophages play proinflammatory and lithogenic roles in nephrolithiasis." (PMID 37051106, 2023). "However, S100A8 and S100A9 were mainly expressed in the renal interstitium of kidney stone patients." (PMID 34395096, 2021). "Therefore, we could make a reasonable conclusion that renal-up-regulated S100A8 and S100A9 in kidney stone patients are predominantly derived from macrophages of M1 type." (PMID 37051106, 2023). "In addition, S100A8 and S100A9 were detected in the renal interstitium of kidney stone patients, which may originate from macrophages in the kidney." (PMID 34395096, 2021). "However, how S100A8 and S100A9 participate in kidney stone formation is unknown." (PMID 37051106, 2023).
Lung Injury (5 papers, 2013 to 2026). "This is supported by previous findings showing that S100A8 triggers IL-6 and MCP-1 production and neutrophil recruitment through TLR4 activation in alveolar epithelial cells, exacerbating inflammation in models of acute lung injury." (PMID 40723384, 2025).